GDPD3 (glycerophosphodiester phosphodiesterase domain containing 3)
Description:
Hydrolyzes lysoglycerophospholipids to produce lysophosphatidic acid (LPA) and the corresponding amines. Shows a preference for 1-O-alkyl-sn-glycero-3-phosphocholine (lyso-PAF), lysophosphatidylcholine (lyso-PC) and N-acylethanolamine lysophospholipids. Does not display glycerophosphodiester phosphodiesterase activity, since it cannot hydrolyze either glycerophosphoinositol or glycerophosphocholine.
Synonyms: GDE7; MGC4171
Tractability: Antibody: UniProt predicts a signal peptide or a membrane-spanning region.
Gene: Protein-coding gene on chromosome 16 (30,104,810 to 30,113,537, reverse strand). Ensembl gene ENSG00000102886.
Subcellular location: Membrane; Cytoplasm, perinuclear region; Endoplasmic reticulum
Subcellular location (Human Protein Atlas): Nucleoplasm; Cytokinetic bridge; Cytosol
Pathways (Reactome):
Metabolism: Glycerophospholipid catabolism
Gene Ontology:
Molecular function: phosphoric diester hydrolase activity; phosphatidylcholine lysophospholipase activity
Biological process: N-acylethanolamine metabolic process; glycerophospholipid catabolic process; lipid metabolic process; phosphatidylcholine catabolic process; phospholipid metabolic process
Cellular component: endoplasmic reticulum; extracellular exosome; endoplasmic reticulum membrane; membrane; perinuclear region of cytoplasm
Genetic constraint (gnomAD): Loss-of-function variants: 40 observed, 44.3 expected, observed/expected ratio (o/e) 0.9, 90% interval 0.7 to 1.17. The upper end of that interval is the gene's LOEUF score, 1.17, which puts it in group 5 of 6, group 1 being the genes least tolerant of losing a copy. Missense variants: 363 observed, 431.4 expected, observed/expected ratio (o/e) 0.84, 90% interval 0.77 to 0.92. Synonymous variants: 145 observed, 164.22 expected, observed/expected ratio (o/e) 0.88, 90% interval 0.77 to 1.01.
Homologues: Orthologues: chimpanzee GDPD3 (99% identical), macaque GDPD3 (95% identical), rabbit GDPD3 (84% identical), pig GDPD3 (78% identical), guinea pig GDPD3 (77% identical), mouse Gdpd3 (76% identical), rat Gdpd3 (75% identical), dog GDPD3 (74% identical), zebrafish gdpd3b (46% identical), zebrafish gdpd3a (46% identical). Paralogues in human: GDPD1 (40% identical), GDPD4 (18% identical), GDE1 (17% identical), GDPD5 (17% identical), GDPD2 (16% identical).
Diseases named in the same sentence as GDPD3 in open-access papers:
GDPD3 is named in the same sentence as 15 diseases in open-access papers, as found by Europe PMC text mining. Sharing a sentence is not in itself a finding about the gene and the disease. The quoted sentences say what the papers report.
chronic myelogenous leukemia (4 papers, 2020 to 2023). "Here, we show that disruption of the Gdpd3 gene encoding a lysophospholipase D enzyme significantly decreased self-renewal capacity in murine chronic myelogenous leukaemia (CML) stem cells in vivo." (PMID 32943626, 2020). "In cancer research, disruption of the GDPD3 gene significantly decreased the self-renewal capacity in murine chronic myelogenous leukemia (CML) stem cells in vivo." (PMID 36837912, 2023). "GDPD3 is necessary to maintain the stem cells of chronic myelogenous leukemia (CML)." (PMID 37004045, 2023).
leukaemia (2 papers, 2020 to 2023). "In contrast, at 40–60 days post-BMT in mice treated with dasatinib, the frequency of BCR-ABL1/EGFP+ leukaemia cells was significantly decreased in PB of Gdpd3−/− retro-CML-affected mice compared to PB of Gdpd3+/+ retro-CML-affected mice." (PMID 32943626, 2020). "Thus, Gdpd3−/− retro-CML-LSK cells do have the ability to give rise to BCR-ABL1/EGFP-expressing mature leukaemia cells." (PMID 32943626, 2020). "At 16–24 days post-BMT, we found no apparent differences in leukaemia cell numbers between Gdpd3+/+ retro-CML-affected and Gdpd3−/− retro-CML-affected mice that had not been treated with dasatinib." (PMID 32943626, 2020). "To determine if this increased survival of BMT recipients bearing Gdpd3−/− retro-CML-LSK cells was due to an inability to produce mature leukaemia cells, we used flow cytometry to examine the frequency of BCR-ABL1/EGFP+ mature leukaemia cells in peripheral blood (PB)." (PMID 32943626, 2020). "However, although BCR-ABL1/EGFP+ leukaemia cells were still present in PB of dasatinib-treated Gdpd3+/+ retro-CML-affected mice, they were dramatically decreased in PB from dasatinib-treated Gdpd3−/− retro-CML-affected mice." (PMID 32943626, 2020).
psoriasis (2 papers, 2023). An autoimmune condition characterized by red, well-delineated plaques with silvery scales that are usually on the extensor surfaces and scalp. "Although indirectly, these studies demonstrate a role for GDPD3 on psoriasis pathogenesis." (PMID 36837912, 2023).
Hepatic steatosis (1 paper, 2023). Steatosis is a term used to denote lipid accumulation within hepatocytes. "Individuals with hepatic steatosis have an increased expression of GDPD3, which was related to the accumulation of triacylglycerol in the liver compared with healthy individuals." (PMID 36837912, 2023).
prostate adenocarcinoma (1 paper, 2025). "In this study, we integrated single-cell and bulk transcriptomic data to construct a 21-gene prognostic model for prostate adenocarcinoma (PRAD), identifying GDPD3 as a key gene associated with tumor progression." (PMID 41562071, 2025).
prostate carcinoma (1 paper, 2025). A carcinoma that arises from epithelial cells of the prostate gland. "This study underscores key molecular mechanisms underlying prostate cancer progression, with GDPD3 emerging as a potential therapeutic target." (PMID 41562071, 2025). "Building on this observation, we conducted a series of functional and mechanistic studies to elucidate the role of GDPD3 in prostate cancer progression." (PMID 41562071, 2025). "Lastly, while we explored the role of GDPD3 in LPA/LPAR1/AKT signaling, further mechanistic studies are needed to fully elucidate its contribution to prostate cancer progression." (PMID 41562071, 2025).
tumor (6 papers, 2018 to 2025). "Clinical validation confirmed its upregulation in tumor tissues, and functional assays demonstrated that GDPD3 promotes cell proliferation, migration, and invasion." (PMID 41562071, 2025). "Clinical validation included comparison of tumor and adjacent normal tissues, revealing significantly elevated GDPD3 expression, further confirmed by immunohistochemistry." (PMID 41562071, 2025). "First, we detected the mRNA expression of 21 risk genes and found that GDPD3, ITGAX, and FAM167B were significantly overexpressed in tumor tissues." (PMID 41562071, 2025). "Knockdown of GDPD3 inhibited tumor cell proliferation, invasion, and migration." (PMID 41562071, 2025). "Mechanistically, GDPD3 regulated the levels of lysophosphatidic acid (LPA), which in turn induced EMT in tumor cells." (PMID 41562071, 2025).
cancer (5 papers, 2015 to 2023). A tumor composed of atypical neoplastic, often pleomorphic cells that invade other tissues. "A significant (p<0.05) association of the expression of GDPD3 or SPRED1 to cancer specific survival from these data was not identified by Cox proportional hazard modeling across these three datasets." (PMID 26230923, 2015).
GDPD3 also shares sentences with these, for which no sentence is quoted: breast carcinoma (2 papers); acute liver failure (1); hearing loss (1); insomnia (1); liver disease (1); migraine (1); Obesity (1).